TBC1D23 (TBC1 domain family member 23)
Description:
Putative Rab GTPase-activating protein which plays a role in vesicular trafficking. Involved in endosome-to-Golgi trafficking. Acts as a bridging protein by binding simultaneously to golgins, including GOLGA1 and GOLGA4, located at the trans-Golgi, and to the WASH complex, located on endosome-derived vesicles. Together with WDR11 complex facilitates the golgin-mediated capture of vesicles generated using AP-1. Plays a role in brain development, including in cortical neuron positioning (By similarity). May also be important for neurite outgrowth, possibly through its involvement in membrane trafficking and cargo delivery, 2 processes that are essential for axonal and dendritic growth (By similarity). May act as a general inhibitor of innate immunity signaling, strongly inhibiting multiple TLR and dectin/CLEC7A-signaling pathways. Does not alter initial activation events, but instead affects maintenance of inflammatory gene expression several hours after bacterial lipopolysaccharide (LPS) challenge (By similarity).
Synonyms: NS4ATP1; FLJ11046; PCH11
Tractability: PROTAC: ubiquitination databases record sites on it; its protein half-life has been measured.
Gene: Protein-coding gene on chromosome 3 (100,260,780 to 100,325,251, forward strand). Ensembl gene ENSG00000036054.
Subcellular location: Golgi apparatus, trans-Golgi network; Cytoplasmic vesicle
Subcellular location (Human Protein Atlas): Golgi apparatus
Gene Ontology:
Molecular function: protein binding
Biological process: brain development; retrograde transport, endosome to Golgi; embryonic brain development; neuron projection development; vesicle-mediated transport; animal organ development; nervous system development
Cellular component: cytoplasmic vesicle; Golgi apparatus; trans-Golgi network; WASH complex; cytosol
Genetic constraint (gnomAD): Loss-of-function variants: 22 observed, 35.63 expected, observed/expected ratio (o/e) 0.62, 90% interval 0.44 to 0.88. The upper end of that interval is the gene's LOEUF score, 0.88, which puts it in group 3 of 6, group 1 being the genes least tolerant of losing a copy. Missense variants: 360 observed, 419.2 expected, observed/expected ratio (o/e) 0.86, 90% interval 0.79 to 0.94. Synonymous variants: 145 observed, 146.55 expected, observed/expected ratio (o/e) 0.99, 90% interval 0.86 to 1.14.
Homologues: Orthologues: pig TBC1D23 (98% identical), chimpanzee TBC1D23 (98% identical), guinea pig TBC1D23 (96% identical), dog TBC1D23 (95% identical), rat Tbc1d23 (95% identical), mouse Tbc1d23 (95% identical), macaque TBC1D23 (93% identical), rabbit TBC1D23 (88% identical), tropical clawed frog tbc1d23 (82% identical), zebrafish tbc1d23 (76% identical), Drosophila melanogaster TBC1D23 (45% identical), Caenorhabditis elegans tbc-1 (29% identical).
Diseases named in the same sentence as TBC1D23 in open-access papers:
TBC1D23 is named in the same sentence as 20 diseases in open-access papers, as found by Europe PMC text mining. Sharing a sentence is not in itself a finding about the gene and the disease. The quoted sentences say what the papers report.
pontocerebellar hypoplasia (4 papers, 2020 to 2024). Pontocerebellar hypoplasias (PCH) are a rare heterogeneous group of diseases characterized by hypoplasia and atrophy and/or early neurodegeneration of the cerebellum and pons. "Here, we show that TBC1D23, a Golgi-localized protein that is frequently mutated in the neurodevelopment disorder pontocerebellar hypoplasia (PCH), is specifically required for the LKB1 signaling at the Golgi." (PMID 38413626, 2024). "Emphasizing the importance of TBC1D23 in human development, homozygous mutations of the TBC1D23 gene has recently been found in patients diagnosed with pontocerebellar hypoplasia (PCH)." (PMID 32258039, 2020). "Two variants in SEPSECS (c.1274A > G:p.H425R) and TBC1D23(c.458T > C:p.M153T), had been reported in gnomAD or ExAC databases; however, no publications have ever reported the pathogenicity of these variants in pontocerebellar hypoplasia." (PMID 38347586, 2024). "Intriguingly, mutations in TBC1D23 lead to pontocerebellar hypoplasia (PCH), a group of rare neurological disorders characterized by impaired development of the brain, especially the pons and cerebellum." (PMID 38413626, 2024). "Emphasizing the importance of TBC1D23 in development and human diseases is the findings that homozygous mutations of the TBC1D23 gene led to pontocerebellar hypoplasia (PCH) and/or intellectual disability." (PMID 32453802, 2020).
lymph node metastasis (1 paper, 2021). "Since IHC indicated that TBC1D23 expression was correlated with lymph node metastasis and TNM stage of NSCLC, we investigated the effect of TBC1D23 on the migration and invasion abilities of NSCLC." (PMID 34363324, 2021).
melanoma (1 paper, 2026). A malignant, usually aggressive tumor composed of atypical, neoplastic melanocytes. "Consequently, loss of TBC1D23 accelerates melanoma progression." (PMID 41748771, 2026). "Here, we report that high TBC1D23 expression correlates with enhanced immune infiltration and favorable prognosis in melanoma." (PMID 41748771, 2026).
tumor (4 papers, 2020 to 2026). "High TBC1D23 expression was correlated with tumour size (p < 0.001), differentiation degree (p < 0.001), metastasis (p = 0.027) and TNM stage (p < 0.001)." (PMID 34363324, 2021). "Next, we analysed 15 pairs of tissue samples (tumour and normal) using Western blotting, revealing higher TBC1D23 expression in tumour tissues than in normal tissues for 12/15 pairs (p = 0.0147)." (PMID 34363324, 2021). "Since IHC indicated that TBC1D23 was positively correlated with NSCLC tumour size, we investigated the effect of TBC1D23 on the proliferation ability of NSCLC." (PMID 34363324, 2021). "Real‐time PCR analysis demonstrated higher TBC1D23 RNA expression in tumour tissues than in normal tissues for 10/15 pairs (p = 0.0195), which suggested that TBC1D23 had a higher transcription level in NSCLC." (PMID 34363324, 2021). "In addition, TBC1D23 has been suggested to be a powerful promoter of tumor cell proliferation, migration, and invasion in non-small cell lung cancer." (PMID 35918393, 2022). "Conversely, TBC1D23 deficiency severely impairs the STING-dependent expression of key IFN-inducible chemokines, suppresses immunostimulatory macrophage maturation, and diminishes the infiltration, activation, and cytotoxic function of tumor-antigen-specific CD8+ T cells." (PMID 41748771, 2026).
cancer (3 papers, 2014 to 2024). A tumor composed of atypical neoplastic, often pleomorphic cells that invade other tissues. "TBC1D23 expression in carcinoma nests was significantly higher than that in normal tissues and was associated with poor prognosis." (PMID 34363324, 2021).
neurological diseases (2 papers, 2020 to 2024). "TBC1D23 is a ubiquitously expressed protein that mutated in the neurological disorder PCH, characterized by abnormal development of the pons and cerebellum." (PMID 38413626, 2024). "Answering these questions will be of interest for the fields of membrane trafficking and neurological diseases, and our current molecular understanding of TBC1D23 lays a foundation for these exciting future discoveries." (PMID 32453802, 2020).
TBC1D23 also shares sentences with these, for which no sentence is quoted: Ataxia (1 paper); atrial septal defect (1); clear cell carcinomas (1); hypothyroidism (1); insulinoma (1); Intellectual disability (1); microcephaly (1); Pneumocystis infection (1); respiratory infections (1); scoliosis (1); Sepsis (1); skin cutaneous melanoma (1); Vertigo (1); Warburg micro syndrome (1).